SYK (spleen associated tyrosine kinase)
Diseases named in the same sentence as SYK in open-access papers (continued):
Sharing a sentence is not in itself a finding about the gene and the disease.
glioma (6 papers, 2018 to 2024). A benign or malignant brain and spinal cord tumor that arises from glial cells (astrocytes, oligodendrocytes, ependymal cells). "Our knowledge of the significance of SIRPB1 and SYK signaling in cancer biology has significantly changed as a result of this interaction's recognition as being important in glioma immune response modulation." (PMID 38594692, 2024). "Although SIRPB1’s functions were initially identified outside of oncological settings, new research highlights the critical role it plays in the glioma immunological landscape, especially when it comes to spleen tyrosine kinase (SYK)." (PMID 38594692, 2024). "SYK significantly impacts the tumor microenvironment and antitumor immunity efficacy, influencing glioma progression by altering cell proliferation and migration pathways." (PMID 38594692, 2024). "In this validation dataset, SYK was highly expressed in the glioma tissues, compared with normal tissues (p < 0.05)." (PMID 35910221, 2022). "We found SYK expression was dramatically higher in higher grade diffuse glioma than in lower grade glioma, in the TCGA cohort (p < 0.05)." (PMID 35910221, 2022). "SYK has been shown to promote the proliferation and migration of glioma cells and recruit macrophages into the tumor microenvironment." (PMID 35910221, 2022). "We also found that high-expression SYK helped to reshape the immunosuppressed glioma microenvironment." (PMID 35910221, 2022). "Recent work in glioma demonstrated that SYK inhibition impaired the mobility and infiltration of B cells and CD11b+ leukocytes in addition to reducing proliferation and migration of tumor cells." (PMID 30744170, 2019). "The colony formation, migration, and proliferation of human and murine glioma samples and cell lines were effectively blocked through SYK inhibition." (PMID 30686982, 2018). "In glioma tissue, diffuse gliomas with high-expression SYK exhibited high-expression CD163 by IHC." (PMID 35910221, 2022). "Therefore, our findings indicate that SYK is involved in remodeling the glioma microenvironment to promote malignant progression." (PMID 35910221, 2022). "Finally, more functional experiments are needed to validate the role of SYK in the glioma microenvironment, especially the immune microenvironment." (PMID 35910221, 2022). "Importantly, when we explored PD-L1 and SYK using the glioma tissue microarrays, a positive correlation was observed (Pearson test, p < 0.05)." (PMID 35910221, 2022). "Therefore, we speculated that both SYK and PD-L1 were expressed by glioma cells and that their expression levels were highly correlated." (PMID 35910221, 2022). "SYK affects the expression of CCL2, IL1RA, and IL8 and participates in the formation of the glioma immune microenvironment, which is considered to be an independent risk factor for glioma patients." (PMID 38594692, 2024). "Notably, investigators found that spleen tyrosine kinase (SYK) activated the PI3K/Akt pathway, further leading to the NF‐κB‐dependent upregulation of M‐CSF in glioma." (PMID 33300633, 2021). "Second, the prognostic value of SYK in gliomas has not been confirmed in the real world." (PMID 35910221, 2022).
IgA nephropathy (6 papers, 2018 to 2025). "The preliminary results of a phase II clinical study of SYK inhibition in IgA nephropathy (NCT02112838) were presented in abstract form at the World Congress of Nephrology meeting in April 2019." (PMID 32305129, 2020). "SYK also mediates proinflammatory responses induced by IgA1 derived from patients with IgA nephropathy, and full results from a Phase II clinical study assessing SYK inhibition with fostamatinib in proliferative IgA nephropathy are awaited (NCT02112838)." (PMID 32305129, 2020). "Clinical studies of SYK inhibition in IgA nephropathy are ongoing, and these novel data suggest that this approach should also be considered in ANCA vasculitis." (PMID 32305129, 2020). "Here, we review the key functions of SYK and the evidence of its contribution to the pathogenesis of IgA nephropathy." (PMID 30177021, 2018). "In renal biopsy specimens of patients with IgA nephropathy, increased expression and phosphorylation of SYK were detected, and this correlated with the histologic features of mesangial and endocapillary proliferation." (PMID 30177021, 2018). "The specific role of SYK in myeloid cells expressing the classic FcαR1 (CD89) in the pathogenesis of IgA nephropathy is less well studied." (PMID 30177021, 2018). "The functional importance of SYK in IgA nephropathy initially was investigated using a cell culture model, wherein human glomerular mesangial cells were stimulated with IgA1 purified from patients with IgA nephropathy." (PMID 30177021, 2018). "It has been reported in the literature that immunohistochemical staining was used to stain the renal tissue of patients with IgA nephropathy, and the results showed that the expression of total SYK and phosphorylated SYK was significantly increased in the glomerulus." (PMID 33389462, 2021). "The results of this clinical trial will be pivotal in understanding whether SYK inhibition may be a safe and effective treatment of IgA nephropathy." (PMID 30177021, 2018). "This review describes the recent scientific evidence, and a current clinical trial, investigating whether spleen tyrosine kinase (SYK) may be a novel and selective therapeutic target for IgA nephropathy." (PMID 30177021, 2018). "Taken together, however, the available preclinical data imply that SYK makes a significant contribution to the pathogenesis of IgA nephropathy, in particular via its role in mediating proinflammatory responses after the deposition of IgA1- and IgG-containing immune complexes in the renal mesangium." (PMID 30177021, 2018). "The SYK inhibitor used in this study, R406 is the orally active metabolite of fostamatinib, which is currently in clinical trials for autoimmune thrombocytopenia, haemolytic anaemia and IgA nephropathy." (PMID 29274344, 2018). "The increased expression of SYK in IgA nephropathy was validated by Ryan et al45 in an independent study, in which they additionally observed that the number of glomerular P-SYK+ cells correlated positively with proteinuria and negatively with renal function in patients with IgA nephropathy." (PMID 30177021, 2018). "Our immunostaining studies suggested co-localization of SYK and CD68+ve in diseased glomeruli in IgA nephropathy, although the functional relevance of these findings to clinical disease will need further investigation." (PMID 30177021, 2018). "The effect of SYK deletion or inhibition has not, to the best of our knowledge, been studied in these possible models of IgA nephropathy." (PMID 30177021, 2018).
mantle cell lymphoma (6 papers, 2017 to 2023). Mantle cell lymphoma is a rare form of malignant non-Hodgkin lymphoma affecting B lymphocytes in the lymph nodes in a region called the ``mantle zone''. "Phosphorylation of several kinases downstream of the BCR such as SYK, LYN and BTK have been noted in primary mantle cell lymphoma (MCL) cells, suggesting constitutively activated BCR signaling in MCL." (PMID 37954584, 2023).
pancreatic cancer (6 papers, 2019 to 2026). "Notably, a separate report indicates that tumor-associated macrophages expressing Siglec-15 in the microenvironment of pancreatic cancer exhibit a distinct immunosuppressive phenotype that is sustained by SYK/MAPK activation associated with Siglec-15." (PMID 37434177, 2023). "Notably, SYK also represents a promising strategy to target TAMs in pancreatic cancer, cells we found to be strongly enriched in the invasive stroma." (PMID 41233595, 2026). "We selected three important target genes (BTK, SYK and BRD4), and tested the anti-tumor effects of their inhibitors on pancreatic cancer cell lines." (PMID 40859234, 2025). "Found a 7 gene panel (MDR1, SRBC, VHL, MUC2, RB1, SYK, and GPC3) that detects colorectal and pancreatic cancers with 63.16% sensitivity, 84% specificity, and AUC of 0.8177." (PMID 36980276, 2023). "In pancreatic cancer, collagen stimulated CXC chemokine ligand-5 (CXCL5) production through the DDR1/PKCθ/spleen tyrosine kinase (SYK)/nuclear factor κB (NF-κB) pathway, which induced neutrophil extracellular traps (NETs) to drive tumor metastasis." (PMID 35935941, 2022).
amyloid (5 papers, 2018 to 2025). "Interestingly, not only do we observe robust SYK upregulation around amyloid plaques (> 3-fold) but associated protein tyrosine phosphatases PTPN6 and INPP5D are also enriched (upregulated 6.0-fold and 2.7-fold respectively)." (PMID 30189875, 2018). "Recently, SYK signaling was shown to be required for the microglial phagocytic clearance of amyloid pathology in a mouse model of AD." (PMID 36945656, 2023).
colitis (5 papers, 2021 to 2023). Inflammation of the colon. "Monoallelic gain-of-function variants in SYK result in systemic inflammation including arthritis, eczema, vasculitis and colitis, several aspects of which were recapitulated in knock-in mice." (PMID 36870198, 2023). "Interestingly, previous studies showed that SYK was associated with the development of DSS-induced colitis (an animal model of ulcerative colitis)." (PMID 37229242, 2023). "The study revealed that mice lacking CARD9 and SYK had impaired activation of inflammatory vesicles and were more susceptible to colitis and CRC." (PMID 37943609, 2023). "Experimental evidence showed that SYK inhibitor significantly alleviated DSS-induced and TNBS-induced colitis by regulating TGFβ, TNFα, and IL-1β, which are also important in the course of PSC." (PMID 37229242, 2023).
follicular lymphoma (5 papers, 2012 to 2023). Follicular lymphoma is a form of non-Hodgkin lymphoma characterized by a proliferation of B cells whose nodular structure of follicular architecture is preserved. "Moreover, we observed that in AT-1 cells, the inhibition of SYK by entospletinib generally downregulates the mTOR pathway, as already described in follicular lymphoma and B-ALL cells." (PMID 31817853, 2019). "mTOR can also be activated in a PI3K-independent manner by spleen tyrosine kinase (SYK), as reported in follicular lymphoma cells." (PMID 23272005, 2012). "TAK‐659, a novel SYK inhibitor, combined with R‐CHOP in patients with newly diagnosed high‐risk DLBCL including DLBCL transformed from follicular lymphoma and DEL, is well tolerated at a dose of 60 mg, with no requirement for dose modification." (PMID 36819145, 2023).
Immunodeficiency (5 papers, 2022 to 2025). Failure of the immune system to protect the body adequately from infection, due to the absence or insufficiency of some component process or substance. "SYK gain-of-function variants found in patients with immune deficiency and systemic inflammation boost immune signaling and elevate inflammatory cytokines." (PMID 40740773, 2025). "Therefore, the relationship between SYK and liver diseases attracts scientists' attention besides the multifactorial role of SYK in immune diseases." (PMID 36568669, 2022). "SYK integrates signals from multiple CLR-dependent and CLR-independent signaling pathways, thus, SYK activation requires a delicate balance whereby a suboptimal response can cause immunodeficiency, whereas an excessive response can lead to hyper-inflammatory disease and hematological malignancy." (PMID 34964702, 2022).
liver fibrosis (5 papers, 2021 to 2024). "In addition, binge alcohol intake could induce SYK activation in an animal study, and SYK was associated with the development of alcoholic liver disease and liver fibrosis." (PMID 33540941, 2021). "For instance, our previous studies demonstrated that targeting SYK of monocyte-derived macrophages effectively alleviates the progression of liver fibrosis." (PMID 39261768, 2024). "One of our previous study showed that targeting SYK of monocyte-derived macrophages alleviates liver fibrosis by remodeling liver inflammatory environment." (PMID 39261768, 2024). "A studies have shown that selective targeting of SYK signaling in myeloid cells protects against liver fibrosis and hepatocarcinogenesis." (PMID 39261768, 2024). "Hepatic stellate cells (HSCs) are considered as the core participants in the deposition of ECM, and several studies have confirmed that the activation of HSCs can be regulated by SYK, which is increased in the development of liver fibrosis and liver cirrhosis." (PMID 36568669, 2022). "Collectively, these studies suggest that SYK is considered as an attractive target for hepatic fibrosis." (PMID 36568669, 2022). "Moreover, the toxin-induced hepatic fibrosis also can be ameliorated by SYK inhibitors (Piceatannol and PRT062607), and lots of genes related with apoptosis, cell cycle and angiogenesis are affected by these small molecule inhibitors targeting SYK in HSCs." (PMID 36568669, 2022). "Moreover, the process of liver fibrosis is also accelerated by SYK activation, which promotes the development of liver cirrhosis and liver cancer eventually." (PMID 36568669, 2022). "Moreover, based on the function of SYK in different biological processes and signaling pathways, most liver diseases, such as liver fibrosis and liver cancer, are relevant to SYK activity directly." (PMID 36568669, 2022). "The expression of SYK is upregulated in hepatocytes and HSCs during the process of liver fibrosis." (PMID 36568669, 2022). "Therefore, SYK plays an important role in the process form viral hepatitis to liver fibrosis, and it’s considered as an important therapeutic target for different viral hepatitis." (PMID 36568669, 2022). "Therefore, the inhibition of SYK is essential in the treatment of liver fibrosis." (PMID 36568669, 2022). "GS-9973 is a SYK-specific small molecule inhibitor that has been shown to suppress fibrosis and HCC progression in a DEN-induced rat model of liver fibrosis." (PMID 39261768, 2024). "Currently, some SYK inhibitors, such as GS-9973, Piceatannol and PRT062607, have been confirmed to hold important potential against liver fibrosis." (PMID 36568669, 2022). "And spleen tyrosine kinase (SYK), which plays an important role in immune cell signaling pathway, has been reported as a biomarker for HCC and a potential target role for liver fibrosis." (PMID 33714200, 2021). "Inhibition of SYK by piceatannol and PRT062607 inhibits HSC activation after TLR4 ligation, reverses T cell depletion and promotes the expression of protective factors by CD4+ T cells in liver fibrosis." (PMID 37506139, 2023). "On the other side, non-hepatic SYK is also regarded as an important therapy target in liver fibrosis." (PMID 36568669, 2022). "Moreover, both protein and mRNA level of SYK in HSCs and hepatocytes is positively correlated with α-SMA (the maker of liver fibrosis) in liver biopsies from patients and CCL4-induced mice liver fibrosis model." (PMID 36568669, 2022). "Especially, the SYK inhibition decreases the expression of TNF-α and IL-8 and suppresses mTOR signaling pathway as well as oxidative phosphorylation in myeloid cells, which protect from hepatic fibrosis effectively." (PMID 36568669, 2022).
periodontitis (5 papers, 2020 to 2025). An acute or chronic inflammatory process that affects the tissues that surround and support the teeth. "Massive DAMPs released by oral epithelial cells inhibit M2 polarization via Mincle/SYK signals and Mincle can be a promising target for the prevention and treatment of periodontitis." (PMID 35251521, 2022). "We showed that the genetic deletion of SYK in LysM‐Cre‐expressing cells suppresses alveolar bone resorption in Sh3bp2KI/+ mice with ligature‐induced periodontitis." (PMID 32537546, 2020). "To date, the role of Mincle/SYK in periodontitis is unclear." (PMID 35251521, 2022). "We found that 200 mg/kg GS‐9973 reduces alveolar bone loss in female Sh3bp2KI/+ mice, but not in males, with periodontitis, suggesting that SYK activation is more critical in female Sh3bp2KI/+ osteoclasts to regulate bone resorption in ligature‐induced periodontitis." (PMID 32537546, 2020). "Furthermore, myeloid cell-specific SYK deletion decreased ligature-induced periodontitis without affecting both inflammatory cytokine expression and osteoclast induction." (PMID 34445604, 2021).
Stroke (5 papers, 2018 to 2023). Sudden impairment of blood flow to a part of the brain due to occlusion or rupture of an artery to the brain. "In summary, microglial TREM-1 receptor yielded post-stroke neuroinflammatory damage via associating with SYK." (PMID 31324751, 2019). "Blockade of TREM-1 can inhibit TREM-1/SYK pathway activation and subsequent inflammatory responses, rescuing stroke outcomes." (PMID 31324751, 2019). "In recent years, studies about the role of SYK gene in stroke have attracted great research interest." (PMID 30499219, 2019). "The biological consequence of altered expression of miR‐129‐2‐3p and SYK in stroke warrants further investigation." (PMID 30499219, 2019). "The opposite direction of change in SYK and miR‐129‐2‐3p expression in stroke further validated our hypothesis that SYK expression might be negatively regulated by miR‐129‐2‐3p." (PMID 30499219, 2019). "TREM1 can recruit spleen tyrosine kinase (SYK) and interacting with SYK, which could launch downstream pro-inflammatory pathways after stroke, and inhibition of TREM1 could exert neuroprotective effects in stroke." (PMID 34721438, 2021).
cutaneous lupus erythematosus (4 papers, 2021 to 2024). An autoimmune disorder that manifests as different lupus-specific skin disorders; it can occur with systemic lupus erythematosus, or as a singular disease. "The immunoregulator spleen tyrosine kinase (SYK) is upregulated in cutaneous lupus erythematosus (CLE)." (PMID 33336508, 2021). "Active, phosphorylated SYK has been observed in tissues from patients with SLE or cutaneous lupus erythematosus, and its inhibition is hypothesized to ameliorate disease pathogenesis." (PMID 33781343, 2021). "Additionally, SYK transcript levels are significantly elevated in keratinocytes of patients with cutaneous lupus erythematosus (CLE) compared to healthy control subjects." (PMID 33781343, 2021).
endometriosis (4 papers, 2021 to 2025). The growth of functional endometrial tissue in anatomic sites outside the uterine body. "Machine learning identified SSTR5, CASP3, FABP2, and SYK as critical targets, contributing to a nomogram that demonstrated good predictive performance for endometriosis risk." (PMID 39754173, 2025). "Four common key targets (SSTR5, CASP3, FABP2, and SYK) were identified across all three machine learning methods, suggesting their crucial role as therapeutic targets for the anti-endometriosis effects of monoterpene glycosides from Paeonia lactiflora." (PMID 39754173, 2025). "The expression profiles of the four key anti-endometriosis targets (SSTR5, CASP3, FABP2, and SYK) were analyzed." (PMID 39754173, 2025). "The correlation between gene expression of the four key anti-endometriosis targets (SSTR5, CASP3, FABP2, and SYK) and immune cell infiltration was analyzed." (PMID 39754173, 2025). "These correlation analyses underscore the significant involvement of the key anti-endometriosis targets (SSTR5, CASP3, FABP2, and SYK) in modulating immune cell infiltration and immune-related pathways." (PMID 39754173, 2025). "qRT-PCR was carried out using the total RNA that was extracted from 10 pairs of normal endometrium and EM tissues and showed higher expressions of BIN2, CCR5, and MRC1 and lower expressions of SYK and ADAM12 in endometriosis tissue than in non-endometriosis tissue." (PMID 34295919, 2021).